IFNLR1 (interferon lambda receptor 1)
Description:
The IFNLR1/IL10RB dimer is a receptor for the cytokine ligands IFNL2 and IFNL3 and mediates their antiviral activity. The ligand/receptor complex stimulate the activation of the JAK/STAT signaling pathway leading to the expression of IFN-stimulated genes (ISG), which contribute to the antiviral state. Determines the cell type specificity of the lambda interferon action. Shows a more restricted pattern of expression in the epithelial tissues thereby limiting responses to lambda interferons primarily to epithelial cells of the respiratory, gastrointestinal, and reproductive tracts. Seems not to be essential for early virus-activated host defense in vaginal infection, but plays an important role in Toll-like receptor (TLR)- induced antiviral defense. Plays a significant role in the antiviral immune defense in the intestinal epithelium.
Synonyms: LICR2; IL28RA; CRF2/12; IFNLR; IL-28R1
Tractability: Antibody: its Gene Ontology location is reachable by antibodies, with high confidence; UniProt predicts a signal peptide or a membrane-spanning region. PROTAC: UniProt records ubiquitination sites on it. Other modalities: a drug acting on it is in phase 2 or 3 trials.
Gene: Protein-coding gene on chromosome 1 (24,154,168 to 24,187,959, reverse strand). Ensembl gene ENSG00000185436.
Subcellular location: Membrane
Subcellular location (Human Protein Atlas): Cytosol
Pathways (Reactome):
Immune System: Interleukin-20 family signaling; Other interleukin signaling
Gene Ontology:
Molecular function: protein binding; cytokine receptor activity
Biological process: positive regulation of cellular respiration; regulation of defense response to virus by host; cellular response to virus; cytokine-mediated signaling pathway; defense response to virus; mucosal immune response; negative regulation of cell population proliferation; response to type III interferon; type III interferon-mediated signaling pathway
Cellular component: interleukin-28 receptor complex; membrane; plasma membrane
Genetic constraint (gnomAD): Loss-of-function variants: 28 observed, 49.93 expected, observed/expected ratio (o/e) 0.56, 90% interval 0.41 to 0.77. The upper end of that interval is the gene's LOEUF score, 0.77, which puts it in group 3 of 6, group 1 being the genes least tolerant of losing a copy. Missense variants: 621 observed, 660.42 expected, observed/expected ratio (o/e) 0.94, 90% interval 0.88 to 1. Synonymous variants: 276 observed, 271.57 expected, observed/expected ratio (o/e) 1.02, 90% interval 0.92 to 1.12.
Homologues: Orthologues: chimpanzee IFNLR1 (99% identical), macaque IFNLR1 (94% identical), guinea pig IFNLR1 (65% identical), rabbit IFNLR1 (65% identical), dog IFNLR1 (62% identical), pig IFNLR1 (62% identical), rat Ifnlr1 (61% identical), mouse Ifnlr1 (61% identical), tropical clawed frog ifnlr1 (23% identical), zebrafish crfb2 (12% identical). Paralogues in human: IL20RA (15% identical), IL10RA (14% identical), IFNAR2 (13% identical), IFNAR1 (12% identical), IFNGR1 (12% identical), IL22RA1 (12% identical), IL10RB (11% identical), IL22RA2 (10% identical), IL20RB (10% identical), IFNGR2 (9% identical), F3 (9% identical).
Diseases named in the same sentence as IFNLR1 in open-access papers:
IFNLR1 is named in the same sentence as 57 diseases in open-access papers, as found by Europe PMC text mining. Sharing a sentence is not in itself a finding about the gene and the disease. The quoted sentences say what the papers report.
viral infection (21 papers, 2013 to 2026). "Missense mutations were identified in the IFN-α receptors 1 and 2 (IFNAR1 and IFNAR2), the IFNGR2, the IFNLR1, receptors critical for the response to viral infections." (PMID 41522351, 2026). "Following infection, IFN-λ, a ligand crucial for the resolution of viral infections, is known to bind to its cognate receptor, IFNLR1, in lung epithelia." (PMID 36379255, 2022). "To examine the role of viral infection in IFNLR1 expression, we differentiated macrophages with GM-CSF, followed by infection with influenza PR8." (PMID 34899695, 2021). "Interferon lambda (IFNλ) signaling is a promising therapeutic target against viral infection in murine models, yet little is known about its molecular regulation and its cognate receptor, interferon lambda receptor 1 (IFNLR1) in human lung." (PMID 34899695, 2021). "Overall, these results suggest that IFNLR1 limits viral infection and thereby dampens the inflammatory response." (PMID 34899695, 2021). "Whereas Ifnlr1−/− × Ifnlr1−/− matings resulted in an increase in viral infection in the placenta and fetal heads, Ifnlr1−/− dam × WT C57BL/6 sire matings had a similar viral burden to WT C57BL/6 mice." (PMID 30384472, 2018). "Also, a few IFNLR1 knockout mouse models exist, but has primarily been studied in context of viral infections." (PMID 40012911, 2024). "Therefore, we propose that homeostatic ISGs stimulated by Ifnlr1 expression on IECs play an early protective role against viral infection that preempts viral IFN evasion mechanisms." (PMID 35137688, 2022). "Differences in the resolution of viral infection may be driven by the tropism of these receptors, underscoring the importance of understanding IFNLR1 expression in the human lung." (PMID 34899695, 2021). "Interestingly, expression of the IFN-λ genes in snout homogenates of WT and Ifnlr1−/− mice was only slightly induced after virus infection, whereas expression of the IFN-β gene was induced about tenfold in all mouse strains." (PMID 29651984, 2018). "Cells of the female reproductive tract mucosa express IFNLR1 and thus respond to type III IFNs, a well-known first-line defense against viral infections in mucosal cells." (PMID 36422611, 2022). "The F-box protein is induced after viral infection and in an unbiased screen, FBXO45 binds IFNLR1 that appears to be localized to a region spanning 50 AA within the cytoplasmic domain." (PMID 36379255, 2022). "They engage the mucosal surface-abundant receptor complex, IFN-λ receptor (IFNLR, also known as IL-28R) that consists of two subunits: IFNLR1 and IL10R2 in the initiation of protection against viral infection at mucosal barriers." (PMID 30671058, 2018). "Enhanced viral shedding and tissue levels in Ifnlr1-/- mice are thus reflective of increased unique productive viral infection events as opposed to just enhanced viral replication following an equivalent number of individual infection events." (PMID 38701091, 2024).
influenza infection (12 papers, 2013 to 2025). "Finally, because influenza infection increased IFNLR1 degradation, we evaluated the stability of the IFNLR1-K319R/K320R variant after PR8 infection for 3 h." (PMID 36379255, 2022). "Deletion of the interferon type I receptor Ifnar1 alone leads only to a moderate increase in susceptibility whereas deletion of both Ifnar1 (interferon (alpha and beta) receptor 1) and the Ifnlr1 (Il28ra, interferon lambda receptor 1) gene strongly increased susceptibility to influenza infections." (PMID 25184786, 2014). "Interestingly, peginterferon lambda-1a led to markedly fewer cases of influenza-like symptoms, leukopenia and dose-reductions than peginterferon alpha-2a, though it did cause more hepatobiliary events consistent with IFNLR1 expression in hepatocytes and liver endothelial cells." (PMID 40012911, 2024). "The role of increased IFNLR1 expression in human alveolar macrophages and monocyte-derived macrophages in inhibiting influenza infection has also been described." (PMID 39331702, 2024). "In this study, we have observed that influenza infection triggers IFNLR1 degradation mediated by FBXO45 that targets IFNLR1 for ubiquitination and degradation in epithelia to impair IFN-λ signaling." (PMID 36379255, 2022). "Mutagenesis studies also indicated that expression of a K319R/K320R IFNLR1 variant in cells exhibited reduced polyubiquitination, yet greater stability and proteolytic resistance to FBXO45 and influenza-mediated receptor degradation." (PMID 36379255, 2022). "We observed that IFNLR1 is relatively unstable in the native state and yet further depleted in lung epithelial cells during influenza infection through the UPS, specifically by the SCFFBXO45." (PMID 36379255, 2022). "The IFNLR1 gene is robustly induced after influenza infection in humans, predicting interferon signaling." (PMID 36379255, 2022). "In humans, IFN-λ is the earliest and most profuse interferon produced during influenza infection, triggering its engagement with IFNLR1 in providing host innate immunity." (PMID 36379255, 2022). "Influenza infection significantly decreased IFNLR1 protein at 8 h post infection in both cell types without decreased receptor mRNA." (PMID 36379255, 2022). "The new contributions in this study provide associations between influenza infection of epithelia, FBXO45, and its interaction with IFNLR1 triggering its degradation." (PMID 36379255, 2022). "To understand the upstream effect of influenza infection on IFNLR1 levels, we infected HBEC3KT cells, which are human telomerase reverse transcriptase-immortalized human bronchial lung epithelial cells." (PMID 36379255, 2022). "Here, we show that IFNLR1 is a labile protein in human airway epithelia that is rapidly degraded after influenza infection." (PMID 36379255, 2022). "With increasing MOI of PR8 influenza infection of these cells over 6 h, we observed a significant decrease in IFNLR1 with PR8 infection via flow cytometry." (PMID 36379255, 2022). "We demonstrate that FBXO45, induced in response to influenza infection, mediates IFNLR1 protein polyubiquitination and degradation through the ubiquitin-proteasome system by docking with its intracellular receptor domain." (PMID 36379255, 2022). "We examined the short-term (<12 h) effect of influenza infection on IFNLR1 protein levels in THP-1 macrophages and BEAS-2B lung epithelial cells." (PMID 36379255, 2022). "To examine how IFNLR1 alters the response to influenza infection, we infected IFNLR1-KO macrophages with PR8 and measured the expression of ISGs." (PMID 34899695, 2021). "IFN-lambda (IFNλ) is the most abundant and earliest expressed interferon during influenza infection that via its cognate receptor, interferon lambda receptor 1 (IFNLR1), induces a robust antiviral response by upregulating antiviral genes." (PMID 34899695, 2021).
influenza infection (continued). "FBXO45 was recently shown to be involved in influenza infection by promoting IFNLR1 ubiquitination and degradation, suggesting that FBXO45 may exert potential regulatory functions in virus-host interactions." (PMID 39936917, 2025). "However, IFNLR1 depleted THP-1 had a significantly abrogated influenza media-stimulated ISG response compared to sgCon THP-1 treated with the same media." (PMID 34899695, 2021). "IFNLR1 knockout in the myeloid cell line, THP-1, exhibited reduced interferon responses to either direct or indirect exposure to influenza infection suggesting the indispensability of IFNLR1 for antiviral responses." (PMID 34899695, 2021). "Zinc interferes with IFN-λ3 binding to IFNL receptor 1 (IFNLR1), resulting in decreased antiviral activity and increased viral replication (HCV, influenza) in vitro." (PMID 28513591, 2017). "Thus, the results suggest that degradation of IFNLR1 occurs via polyubiquitination via the SCFFBXO45 E3 ligase, possibly at the K319/K320 molecular site(s) during influenza infection." (PMID 36379255, 2022). "Although we have previously demonstrated the presence of the IFN-λ–IFNLR1 signaling axis in human lung macrophages and its role in combating influenza infection, the expression, signaling, and molecular regulation of IFNLR1 in human bronchial epithelial cells has not been fully elucidated." (PMID 36379255, 2022). "Several studies have shown that mice treated with IFN-λ after influenza infection exhibited significantly lower mortality, decreased viral burden, with reduced inflammatory cytokines compared to control underscoring the indispensability of the IFN-λ–IFNLR1 axis." (PMID 36379255, 2022).
COVID-19 (9 papers, 2020 to 2024). A disease caused by infection with severe acute respiratory syndrome coronavirus 2. "Conversely, none of the IFNRs encoded on chr21 are elevated at the RNA level in patients with COVID-19, who instead display up-regulation of IFNLR1." (PMID 37379383, 2023). "Our results revealed that subsets of immune cells within PBMCs from COVID-19 patients expressed IFNLR1 and were able to respond to PEG-IFN-λ treatment by upregulating ISGs." (PMID 36385011, 2022). "When comparing COVID-19 mild vs critical patients, we identified IFNLR1, IFNA1, CXCL9, CXCL10, IL15 and IL15RA to be upregulated in mild patients." (PMID 33473155, 2021). "Moreover, we found that pregnancies with COVID-19 developed more pronounced inflammatory responses with activation of the IFNL1/IFNLR1 axis, which may trigger perinatal immune activation." (PMID 38267411, 2024). "Another duo of a ligand and its receptor that was upregulated in plasma of severe COVID-19 is IFNL1 (INF lambda 1, type-III INF) and one of its receptors, IFNLR1." (PMID 35177642, 2022). "Overall, these analyses demonstrated that IFNLR1 + immune cells in the peripheral blood responded, in vivo, to PEG-IFN-λ treatment in COVID-19 patients." (PMID 36385011, 2022). "IL7, IL17RC, and IFNLR1 were upregulated in the early stages of COVID-19 while absent in later disease stages." (PMID 35983322, 2022).
psoriasis (8 papers, 2013 to 2025). An autoimmune condition characterized by red, well-delineated plaques with silvery scales that are usually on the extensor surfaces and scalp. "For example, eSNPs influencing IFNLR1 expression colocalize with psoriasis variants (PP.H4 = 0.834) and the lead eSNP rs59960858 is in almost perfect LD (r2 = 0.961) with the psoriasis risk allele rs7552167." (PMID 37805522, 2023).
ZIKV infection (5 papers, 2018 to 2023). "To confirm the hormone dependent effects on IFN-λ activity, we compared ZIKV infection in progesterone only-treated hSTAT2 KI and hSTAT2 KI Ifnlr1−/− mice." (PMID 30655513, 2019). "ZIKV infection also increased expression of mRNAs for both IFNLR1 and IL10RB components of the IFNλ heterodimeric receptor complex and the SOCS1 and SOCS3 negative regulators of IFN signaling." (PMID 31289325, 2019). "Estradiol-treated animals (estrous stage), which showed a thickened epithelial layer, were resistant to intravaginal ZIKV infection in anti-Ifnar1 mAb-treated Ifnlr1−/− and WT mice." (PMID 30655513, 2019). "The increased ZIKV infection in vagina of hSTAT2 KI Ifnlr1−/− mice was localized to the epithelial layer (bottom right)." (PMID 30655513, 2019). "The effects of type III IFNs during ZIKV infection have been evaluated in pregnancy using Ifnlr1−/− dams crossed to WT C57BL/6 or Ifnlr1−/− sires." (PMID 30384472, 2018). "To evaluate this hypothesis, we measured the levels of Ifnlr1, Il10rb, Ifnl2, and Ifnl3 mRNA by RT-qPCR in the vagina on days 1, 4, and 7 after ZIKV infection." (PMID 30655513, 2019). "The disparity of ZIKV infection in Ifnlr1−/− mice after different hormone treatments might be due to differential expression of IFN-λ or its heterodimeric receptor Ifnlr1/Il10rβ." (PMID 30655513, 2019). "Although OVX WT and Ifnlr1−/− mice given both estradiol and progesterone had equivalent ZIKV infection in FRT tissues, we speculated that cells in the vagina might respond to exogenous IFN-λ." (PMID 30655513, 2019). "However, Ifnlr1−/−and WT mice sustain similar levels of ZIKV infection in FRT tissues when animals were treated with estradiol and progesterone (proestrous phase, which corresponds with the hormone profile in the luteal phase of humans), suggesting a hormonal stage-dependent effect of IFN-λ." (PMID 30655513, 2019). "In a mouse model of congenital ZIKV infection, IFN-λ restricted transplacental transmission, as fetuses from Ifnlr1−/− pregnancies (Ifnlr1−/− × Ifnlr1−/−) sustained higher fetal and placental viral loads than those from wild-type (WT) pregnancies." (PMID 35471083, 2022). "We observed statistically significant increases in ZIKV infection in the vagina and uterus and a trend toward greater infection in the cervix at 7 dpi of progesterone only-treated OVX hSTAT2 KI Ifnlr1−/− compared to hSTAT2 KI mice." (PMID 30655513, 2019). "Here, we used mouse models of congenital ZIKV infection to determine the targets of IFN-λ signaling by infecting pregnancies that lacked IFN-λ signaling (Ifnlr1−/−) in maternal and/or fetal tissues." (PMID 35471083, 2022). "RNA ISH also showed relatively equivalent levels of ZIKV infection in the vagina of WT and Ifnlr1−/− mice, without substantive differences in inflammation." (PMID 30655513, 2019). "To assess the effects of IFN-λ signaling on inhibition of ZIKV infection in the FRT during the estradiol phase, we compared intravaginal infection in OVX WT and Ifnlr1−/− mice with or without estradiol treatment." (PMID 30655513, 2019).
hepatoma (3 papers, 2011 to 2021). "In hepatoma cells, IFNL4 gene transfection or recombinant IFN-λ4 protein treatment robustly increased the protein levels of ISG15 and USP18 in an IFNLR1-dependent manner and potently blocked IFN-α signalling." (PMID 28630501, 2017). "Thus, we explored functional effects of both IFN-λ3 and IFN-λ4 in a panel of hepatoma HepG2 cell lines, in which we inducibly expressed IFN-λ3-GFP or IFN-λ4-GFP and used CRISPR-Cas9 gene editing to eliminate IFNLR1, the receptor used by all type III IFNs." (PMID 34497603, 2021).
lupus (3 papers, 2021 to 2023). "To address this conundrum, we used the well-established pristane-induced model of murine lupus in Ifnlr1-deficient mice." (PMID 34769174, 2021). "In a TLR7-induced lupus mouse model, Ifnlr1-deficient mice displayed reduced skin and kidney inflammation as well as decreased immune complex deposition." (PMID 34769174, 2021). "Lupus induced renal pathology was also significantly alleviated in Ifnlr1-/- mice compared to WT animals." (PMID 34899712, 2021). "Intriguingly, their most prominent trans-target is interferon lambda (IFNλ) receptor 1 (IFNLR1), whose deficiency lowers the activation of immune cells and reduces organ damage in kidneys without affecting production of antibodies in murine lupus." (PMID 37475860, 2023). "IFNLR1 deficiency, in addition, reversed the proportion of Eomes+ and Eomes− cells to similar levels as seen in untreated control mice, suggesting that IFN-λ signaling promotes the recruitment of NK cells to the kidneys in murine lupus." (PMID 34769174, 2021).
Rotavirus infection (3 papers, 2021 to 2022). Infection with any of the rotaviruses. "In agreement with earlier studies, we observed that animals lacking functional receptors for type I IFN (Ifnar1-/-), for type III IFN (Ifnlr1-/-) or for both IFN types (DKO) were more susceptible to rotavirus infection compared with WT mice." (PMID 34383769, 2021). "Lastly, we find that IECs lacking Ifnlr1 are hyper-susceptible to initiation of murine rotavirus infection." (PMID 35137688, 2022). "To investigate whether these homeostatic ISGs protect against MRV, we used Ifnlr1 IEC-cKO mice that lack homeostatic ISGs rather than using ABX treatment, which introduces pleiotropic effects on rotavirus infection and dramatically increases transit time through the intestine." (PMID 35137688, 2022).
Autoimmunity (2 papers, 2021 to 2025). The occurrence of an immune reaction against the organism's own cells or tissues. "To study the role of type III IFN in autoimmunity and lupus-like disease, we injected pristane into mice deficient in functional type III IFN receptors (Ifnlr1−/−) and wild-type controls." (PMID 34769174, 2021).
colitis (2 papers, 2021 to 2025). Inflammation of the colon. "In the mouse model of dextran sodium sulfate-induced colitis, knockout of the interferon regulatory factor Irf7 or the interferon-λ receptor (Ifnlr1) gene increased susceptibility to colitis; administration of interferon-λ2 reversed the effect of Irf7 knockout." (PMID 40996888, 2025).